CACNA2D4 (calcium voltage-gated channel auxiliary subunit alpha2delta 4)
Description:
The alpha-2/delta subunit of voltage-dependent calcium channels regulates calcium current density and activation/inactivation kinetics of the calcium channel.
Synonyms: alpha2delta-4; RCD4
Tractability: Small molecule: an approved drug acts on it; a high-quality ligand is known; it belongs to a druggable protein family. Antibody: UniProt predicts a signal peptide or a membrane-spanning region.
Gene: Protein-coding gene on chromosome 12 (1,791,963 to 1,918,666, reverse strand). Ensembl gene ENSG00000151062.
Subcellular location: Membrane
Subcellular location (Human Protein Atlas): Mid piece; Principal piece
Gene Ontology:
Molecular function: voltage-gated calcium channel activity
Biological process: calcium ion transmembrane transport; detection of light stimulus involved in visual perception
Cellular component: voltage-gated calcium channel complex; membrane
Genetic constraint (gnomAD): Loss-of-function variants: 142 observed, 138.89 expected, observed/expected ratio (o/e) 1.02, 90% interval 0.89 to 1.17. The upper end of that interval is the gene's LOEUF score, 1.17, which puts it in group 5 of 6, group 1 being the genes least tolerant of losing a copy. Missense variants: 1,347 observed, 1,382.8 expected, observed/expected ratio (o/e) 0.97, 90% interval 0.93 to 1.02. Synonymous variants: 577 observed, 551.21 expected, observed/expected ratio (o/e) 1.05, 90% interval 0.98 to 1.12.
Gene-disease validity (ClinGen):
ClinGen rates the evidence that CACNA2D4 causes each of these diseases.
CACNA2D4-related retinopathy (autosomal recessive): Definitive. Any retinopathy caused by variants in the CACNA2D4 gene.
Homologues: Orthologues: macaque CACNA2D4 (97% identical), chimpanzee CACNA2D4 (97% identical), dog CACNA2D4 (85% identical), guinea pig CACNA2D4 (84% identical), rat Cacna2d4 (83% identical), mouse Cacna2d4 (83% identical), pig CACNA2D4 (82% identical), tropical clawed frog cacna2d4 (68% identical), zebrafish cacna2d4b (58% identical), zebrafish CACNA2D4 (46% identical), Drosophila melanogaster stj (36% identical), Caenorhabditis elegans unc-36 (18% identical), and 1 more. Paralogues in human: CACNA2D3 (57% identical), CACNA2D2 (29% identical), CACNA2D1 (27% identical), CACHD1 (19% identical).
Diseases named in the same sentence as CACNA2D4 in open-access papers:
CACNA2D4 is named in the same sentence as 30 diseases in open-access papers, as found by Europe PMC text mining. Sharing a sentence is not in itself a finding about the gene and the disease. The quoted sentences say what the papers report.
Cone rod dystrophy (3 papers, 2014 to 2023). "The question as to why humans with mutations in CACNA2D4 have a cone-rod dystrophy remains." (PMID 37181655, 2023).
retinal dystrophies (3 papers, 2023 to 2025). "Pathogenic variants in the CACNA2D4 gene, which encodes the α2δ-4 subunit, researchers observed cone – rod dysfunction in mice and retinal cone dystrophy in humans." (PMID 40129245, 2025). "In humans, mutations in exon 19 and 25 of the CACNA2D4 gene, which encodes α2δ-4 subunits, have been linked to retinal dystrophy." (PMID 40129245, 2025).
retinitis pigmentosa (3 papers, 2019 to 2025). Retinitis pigmentosa (RP) is an inherited retinal dystrophy leading to progressive loss of the photoreceptors and retinal pigment epithelium and resulting in blindness usually after several decades. "Two reports suggested that CACNA2D4 biallelic missense variants could be associated with retinitis pigmentosa." (PMID 40883544, 2025). "Biallelic gene defects in CACNA2D4 (OMIM #608171) have been associated with autosomal recessive cone dystrophy (RCD4, OMIM #610478), nonprogressive retinal dysfunction, and more recently with retinitis pigmentosa and cone-rod dystrophy." (PMID 40883544, 2025).
autism spectrum disorder (2 papers, 2021 to 2023). A spectrum of developmental disorders that includes autism, and Asperger syndrome. "Furthermore, CACNA2D4 has been implicated in autism spectrum disorders, and a deletion in the CACNA2D4 gene was found in a patient with bipolar disorder, but it is unknown if this patient suffers with vision problems." (PMID 37672513, 2023).
bipolar disorder (2 papers, 2019 to 2023). A disorder of the brain that causes unusual shifts in mood, energy, activity levels and the ability to carry out day-to-day tasks. "Mutations in CACNA2D4 can cause retinal dysfunction in humans and a partial deletion of CACNA2D4 was identified in patients with late-onset bipolar disorder." (PMID 30683685, 2019).
adenoma (1 paper, 2020). A neoplasm arising from the epithelium. "More specifically, genes with such a therapeutic potential in non-functioning adenomas included CACNA2D4, IDH1, AURKB, GRIA2, PTGS2 and CX3CR1." (PMID 33168897, 2020). "The expression of genes such as CACNA2D4, GRIA2, miR4774, miR1179 and LINC01351 was found to be up-regulated due to lower methylation rates in non-functioning adenomas." (PMID 33168897, 2020).
attention deficit-hyperactivity disorder (1 paper, 2020). A disorder characterized by a marked pattern of inattention and/or hyperactivity-impulsivity that is inconsistent with developmental level and clearly interferes with functioning in at least two settings (e.g. at home and at school). "For instance, a SNP located between the CACNA2D4 and CACNA1C genes (rs1024582) was significantly associated with cross-disorders that included attention deficit hyperactivity disorder (ADHD), BPD, ASD, SCZ, and MDD." (PMID 32607809, 2020).
autosomal recessive cone rod dystrophy (1 paper, 2017). autosomal cone rod dystrophy is an autosomally recessive inherited retinal dystrophy that belongs to the group of pigmentary retinopathies. "Homozygous mutations in the CACNA2D4 gene have been associated with autosomal recessive cone rod dystrophy and nonprogressive inner retinal cone system dysfunction, but carriers with only one mutation in the CACNA2D4 gene had no symptoms." (PMID 28837078, 2017).
gastric cancer (1 paper, 2021). A primary or metastatic malignant neoplasm involving the stomach. "An analysis of 98 Ca2+-regulating genes from two gene-expression-profiling datasets on gastric cancer, highlighted that CACNA2D4 was associated with either a 40% decrease (Dataset One) or a 2.9-fold increase (Dataset Two) in overall survival." (PMID 36046118, 2021). "A DNA-methylation study showed that CACNA2D4 mRNA expression was upregulated in cultured gastric cancer cell lines, compared to normal stomach cells." (PMID 36046118, 2021).
hyperhomocysteinemia (1 paper, 2025). A serious metabolic condition caused by mutations in the MTHFR gene, medications, or nutritional deficiency. "Cacna2d4 is an L-type voltage-dependent Ca2+ channel auxiliary subunit (α2/δ4) while a marker of AD and hyperhomocysteinemia." (PMID 40979532, 2025).
Hypocalcemia (1 paper, 2019). An abnormally decreased calcium concentration in the blood. "Besides, a number of germline mutations in genes related to calcium metabolism (CACNA2D4, CD36, etc.)and the administration of irinotecan were speculated to be the causes of severe hypocalcemia." (PMID 31510946, 2019).
keratoconus (1 paper, 2025). A degenerative, structural disorder of the eye, characterized by a cone-shaped protrusion of the cornea. "In the corneal samples of patients with keratoconus, calcium voltage-gated channels including CACNA1C, CACNA1G, CACNA2D1, and CACNA2D4 were found to be down-regulated that could be indicative of reduced cell proliferation as observed in keratoconus." (PMID 39420106, 2025). "As a consequence, down-regulated voltage-gated calcium channels in CACNA1C, CACNA1G, CACNA1D1, and CACNA2D4, and purinergic receptors P2RX1 along with the down- regulated transcription factors including JUN and MYC can be attributed to reduced cell proliferation in keratoconus." (PMID 39420106, 2025).
Optic disc pallor (1 paper, 2021). A pale yellow discoloration of the optic disc (the area of the optic nerve head in the retina). "Optic disc pallor has not been described in cases of iCSNB due to CABP4 or CACNA2D4 mutations." (PMID 33668843, 2021).
status epilepticus (1 paper, 2022). Status epilepticus is defined as a continuous seizure lasting more than 30 min, or two or more seizures without full recovery of consciousness between any of them. "However, mutations in CACNA2D4 in patients with neurodevelopmental disorders and increased α2δ-4 mRNA expression levels in the hippocampus after status epilepticus suggest previously unrecognized functions in the brain." (PMID 36077281, 2022).
uveal melanoma (1 paper, 2021). A melanoma derived from melanocytes of the uveal tract. "Similar to our findings, CACNA2D4 was one of the few genes associated with the metastasis of uveal melanoma." (PMID 36046118, 2021).
viral infection (1 paper, 2013). "Using a sorting approach independent from genetically encoded fluorochromes with Cacna2d4 or Cnga1, for example, to enrich in vitro generated photoreceptors would avoid the need for viral infection and genetic manipulation of donor cells, and lead to easier clinical application." (PMID 24146539, 2013).
tumor (4 papers, 2016 to 2022). "Five genes, CACNB4 (FCMSS 0.65), MAP3K6 (FCMSS 0.66), CD14 (FCMSS 0.66), CACNA2D4 (FCMSS 0.66), and MAP4K4 (FCMSS 1.52) had slightly stronger FC for MSS-specific tumors than for all tumor combined (FCoverall 0.67, 0.73, 0.68, 0.67, and 1.47, respectively)." (PMID 29636593, 2018). "An abridged list contains 23 hypermethylated genes and 4 hypomethylated genes (CACNA2D4;LRTM2, ESPNL, SECTM1, PCDH8) for AA tumor samples; whereas, 29 hypermethylated genes and 1 hypomethylated gene (BRSK2) are listed for the CA tumor samples." (PMID 27111221, 2016).
cancer (2 papers, 2021 to 2022). A tumor composed of atypical neoplastic, often pleomorphic cells that invade other tissues. "It would also be valuable to know whether there are any synergistic effects between CACNA2D4 and CACNA2D3; the literature points to each gene having opposing roles in the cancers." (PMID 36046118, 2021).
neurodevelopmental disorder (2 papers, 2022). A behavioral and cognitive disorder with onset during the developmental period that involves impaired or aberrant development of intellectual, motor, or social functions. "Variants in the CACNA2D4 gene encoding the α2δ-4 auxiliary subunit of these channels are associated with neuropsychiatric and neurodevelopmental disorders." (PMID 35353835, 2022).
neurological disorders (1 paper, 2021). "Accordingly, alterations to voltage‐gated calcium channel genes, including CACNA2D4, have been implicated in human psychiatric and neurological disorders." (PMID 33098150, 2021).
retinopathy (1 paper, 2024). "Several candidate genes associated with CQ/HCQ retinopathy were found with exome sequencing, including RP1L1, RPGR, RPE65, CACNA2D4, EYS, RP1, IMPG1 and ABCA4." (PMID 38548946, 2024).
CACNA2D4 also shares sentences with these, for which no sentence is quoted: infection (2 papers); retinal degeneration (2); congenital stationary night blindness (1); diabetes (1); dilated cardiomyopathy (1); familial atrial fibrillation (1); mammary tumours (1); pancreatic adenocarcinoma (1); retinal diseases (1).